PCNA (proliferating cell nuclear antigen)
Diseases named in the same sentence as PCNA in open-access papers (continued):
Sharing a sentence is not in itself a finding about the gene and the disease.
tumor (continued). "It is important to emphasize that while either sirolimus or temsirolimus can induce prolonged proliferative arrest based on the absence of PCNA staining, we did not detect cleaved caspase 3 in treated tumor cells, indicating that neither agent is cytotoxic as a single agent." (PMID 34331013, 2021). "Moreover, the IHC assay indicated that the levels of proliferation-related protein (Ki-67 and PCNA) were lower and the level of EMT-related protein (E-cadherin) was higher in tumor specimens of the GEM combined with DET group compared with those of the other three groups." (PMID 32526702, 2020). "Moreover, a significant decrease in the following parameters has been reported, proliferating cell nuclear antigen (PCNA) index, glutathione S-transferase placental positive foci (GST-P), tumor biomarkers in serum besides reduction of inflammation, angiogenesis and metastasis in HCC." (PMID 32630505, 2020). "Immunostaining analysis for PCNA showed a lower number of proliferating hepatocytes in the tumor and non-tumor regions of Atg7/Hmgb1ΔHep livers than those in the Atg7ΔHep livers, suggesting that HMGB1 contributed to an overall enhanced proliferation status in autophagy-deficient livers." (PMID 32382012, 2020). "Consistently, we now found that Atg7ΔHep livers had a remarkably increased number of hepatocytes positive for proliferation of cell nuclear antigen (PCNA) or Ki67, which seemed to be present in both non-tumor and tumor regions without much differences in the level." (PMID 32382012, 2020). "Analysis of WT and Casp11−/− colons at the 6 week tumour development stage revealed significantly increased IEC proliferation in Casp11−/− colons compared with treatment matched WT colons, as assessed by staining and histological evaluation of the proliferation markers PCNA and Ki67." (PMID 30538296, 2019). "Of interest, we could not detect any changes in the number of PCNA-positive cells, indicating that treatment with the different embolics in the present study did not influence tumor cell proliferation." (PMID 31601175, 2019). "Using immunocytochemical techniques, some researchers have demonstrated that hypoxic tumor cells are in a non- or slow-proliferating state and a majority of these cells are negative for proliferation markers, such as Proliferating Cell Nuclear Antigen (PCNA) or Bromodeoxyuridine (BrdU)." (PMID 31484342, 2019). "Eight weeks after tumor cell inoculation, immunohistochemistry was used to assess the therapeutic efficacy according to microvessel density (MVD), proliferating cell nuclear antigen (PCNA), and terminal‐deoxynucleotidyl transferase‐mediated nick‐end labeling (TUNEL) assays." (PMID 29659181, 2018). "In addition, immunohistochemical analysis of tumor tissues from each group showed an increased number of TUNEL-positive cells and reduced proliferating cell nuclear antigen (PCNA) signals in TCS+GrzB group compared with the control, TCS only and GrzB only groups." (PMID 28460437, 2017). "Furthermore, immunohistochemistry analysis revealed that PCNA, ABCG2, and OCT4 were positive in the tumor tissues caused by K3-SP but negative in the tumor tissues caused by K3-NSP." (PMID 28465472, 2017). "Additionally, there was a reduction in VEGF in the tumor sections and no apparent changes in PCNA or γH2AX staining in heart and kidney sections respectively for both groups." (PMID 28439094, 2017). "Scribfl/flAlbCre liver tumors also displayed increased proliferation as revealed by PCNA staining, but no detectable apoptosis, indicating that the increased tumor growth in Scribfl/flAlbCre mice was due to increased proliferation rather than changes in apoptosis." (PMID 28460446, 2017). "Most FLAG and PCNA expression was detected in cancer cells, with obvious colocalization, in cancer cells in the tongues of DOX+ iDek mice treated with 4NQO, indicating that DEK may interact with PCNA in cancer cells during tumor progression." (PMID 28834425, 2017).
tumor (continued). "Furthermore, the decrease in PCNA protein level and the increase in cleaved-PARP protein level were observed in tumor tissue using Immunohistochemistry and Western blotting analyses, while the level of Bcl-2 protein did not change (**P < 0.01, ****P < 0.0001, vs control)." (PMID 26811493, 2016). "IHC staining of Ki-67 and proliferating cell nuclear antigen (PCNA) was performed on the tumors and, in comparison to the negative control, upregulation of CXCL1 significantly promoted proliferation, as indicated by the number of tumor cells positive for Ki-67 and PCNA staining." (PMID 27542259, 2016). "Moreover, given that CEA and proliferating cell nuclear antigen are closely related, CEA may also be involved in tumor cell proliferation." (PMID 27147574, 2016). "In addition, the percentage of tumor-infiltrating PCNA-negative inflammatory cells in stroma areas was determined for each patient." (PMID 26147201, 2015). "PCNA, a 36-kDa non-histone nucleoprotein that is synthesized at the G1 and S phases of the cell cycle and is directly involved in DNA synthesis by acting as a cofactor of DNA polymerase δ, is a one of the most common indicators of tumor proliferation kinetics." (PMID 25667616, 2015). "Moreover, immunohistochemical staining revealed that miR-320a overexpression reduced integrin β3 expression by more than 60% but did not influence the percentage of proliferative PCNA+ tumor cells." (PMID 25924850, 2015). "However, correlation between tumor size and p-Akt levels as well as PCNA persists independent of genotype." (PMID 26345456, 2015). "In order to understand how PFEC induced apoptosis of tumor cells and inhibited cell proliferation, we detected gene expression of cell growth and anti- and pro-apoptosis genes such as Akt, PI3K, Bcl-2, Bcl-xL, Bax, Bid and cell proliferation gene cyclin D1 and PCNA in cells by quantitative PCR." (PMID 25029345, 2014). "The growth inhibition and the possible induction of tumour regression by ACV-TP-T correlated with the reduction of the proliferative activity and increased frequency of apoptotic liver cells as measured by immunostaining detection of PCNA and activated caspase 3, respectively." (PMID 24862448, 2014). "However, propranolol as a stand-alone therapeutic (like most therapeutics) did not completely abolish tumor cell proliferation as evidenced by positive PCNA staining in propranolol treated tumors." (PMID 23555867, 2013). "In addition, TIM-3 was co-expressed with Bcl-2 and PCNA, indicating that TIM-3 may regulate tumor cell apoptosis and proliferation." (PMID 24137353, 2013). "Although CENP-A correlates with Ki-67, overexpression of CENP-A independent of the higher proliferation rates of tumor cells is further supported by the observations of Tomonga and colleagues that the level of proliferating cell nuclear antigen (PCNA) was generally similar in tumor and normal cells." (PMID 22559056, 2012). "The present work aimed at evaluating the tumor suppressive effects of MSCs on the in vivo progression of HCC, and to investigate the possible role of Wnt signaling in tumor tissues by assessing the gene expression profile of some of the Wnt signaling target genes:cyclin D, PCNA, survivin, β-catenin." (PMID 21545718, 2011). "Previous studies demonstrated that p21 could act as a "tumor suppressor" by binding to cellular CDK and proliferating cell nuclear antigen (PCNA), thereby inhibiting their function and leading to cell cycle arrest, leading to blockade of DNA synthesis and inhibition of cell proliferation." (PMID 21933447, 2011). "Two weeks after the final injection of the TLR4/9 agonist complex, the expression of activated caspase-3 and PCNA in the lung tissue of the mice treated with the immune complex was similar to that in the mice treated with PBS in the absence of tumor cell inoculation." (PMID 21931823, 2011).
tumor (continued). "We performed PCNA staining (a marker of cells in early G1 and S phase) of PND84 tumors in selected sections of Cdh11+/+;TAg+/- (n = 2) and Cdh11-/-; TAg+/- (n = 2) mice and calculated the percent PCNA positive cells per tumor volume revealing little difference between the two genotypes." (PMID 20421947, 2010). "Clinical research has revealed that although the lymphatic vessels in the tumor mass are PCNA-positive, they may not be functional since they usually consist of a low number of small and flattened endothelial cells." (PMID 19232130, 2009). "It is noteworthy that we observed only a weak-to-moderate association between DKC1 levels and actual markers of tumour proliferation, such as MKI67 and PCNA, suggesting that the increase in DKC1 expression is not simply a by-product of enhanced cell proliferation." (PMID 19755982, 2009). "Additionally, the study focused solely on Ki-67, and incorporating other proliferative markers (such as proliferating cell nuclear antigen as PCNA and minichromosome maintenance protein-2 as MCM-2) could provide a more comprehensive assessment of tumor behavior." (PMID 41583280, 2025). "In addition, protein expression of PCNA, CyclinD1, Bcl-2, Integrin α2/β1, p-FAK, p-PI3K (p85), p-AKT, p-mTOR, C-myc proteins were also significantly increased in the DLD-1 xenograft tumor treated with S. moorei and were reversed by RGD peptides in S. moorei-treated DLD-1 xenograft tumor." (PMID 39990665, 2025). "Furthermore, tumour tissues originating from PANC‐1 cells treated with exosomes had higher KI67 and PCNA expression than those originating from control cells, whereas KI67 and PCNA expression was reduced in tumour tissues derived from PANC‐1 cells with tRF‐19‐PNR8YPJZ‐knockdown." (PMID 37488774, 2023). "However, PCNA expression did not significantly correlate with tumor stages of patients with NSCLC." (PMID 33658396, 2021). "The expression of PCNA, VEGF, MMP‐2, and MMP‐9 in Diet I+NDEA and Diet II+NDEA groups was significantly lower than in the NDEA group (p < 0.01 or p < 0.05), indicating that Diet I and Diet II could inhibit cancer proliferation and affect tumor neovascularization, invasion, and metastasis." (PMID 30680188, 2019). "However, the percentage of PCNA-positive cells was significantly reduced in TAM-treated combination group compared to all the other treatment groups, suggesting this combinatorial regimen further consolidates the anti-tumor effect of TAM treatment by inhibiting tumor cell proliferation." (PMID 28839265, 2017). "Furthermore, we found that the PCNA level was negatively correlated to the Smad3 level, suggesting that downregulation of Smad3 may contribute to the inactivation of TGF-β signaling and the promotion of tumor growth." (PMID 24636138, 2014). "Interestingly, the uptake of [11C]-methionine correlates with Ki-67 and proliferating cell nuclear antigen expression and with microvessel count in proliferating cells, suggesting that [11C]-MET uptake may represent a biological marker for tumour proliferation and neoangiogenesis." (PMID 24649372, 2014). "To validate the possibility to use the Dnmt1/PCNA P-LISA to evaluate the degree of DNA hypomethylation in cells, we compared whether the number of Dnmt1/PCNA interactions was correlated with the values of 5 mC number quantification (ELISA method) in non-tumor and tumor breast cell lines." (PMID 21470401, 2011). "Using two model systems we have shown that PCNA is induced in non-cycling cells by adjacent transplanted tumour cells and that this phenomenon may be mimicked by the in vivo administration of growth factors (transforming growth factor alpha and epidermal growth factor)." (PMID 7914422, 1994).
tumor (continued). "To explain this arrest, we focused on the proliferating cell nuclear antigen (PCNA), whose expression level and redox state have been described to be altered by the lack of PRDX6 in other tumor cell lines." (PMID 39061949, 2024). "Furthermore, significantly fewer Ki67+/PCNA+ tumor cells were found in the surrounding brain tissues of the t0-, t12-, or t24-irradiated tumors than in the nonirradiated tumors, indicating that these tumor cells have a lower proliferation potential away from the irradiated in situ tumors." (PMID 37150786, 2023). "The present study also revealed a positive correlation between DAND5 and the two proliferation markers (PCNA and Ki67) in HER2 positive tumours but not in other subtypes." (PMID 37333824, 2023). "The immunoreactivity for pan-keratin, vimentin, CD34 and PCNA was positive, but INI-1 was negative in the organoids similar to the original EPS tumor tissue and xenograft tumors." (PMID 35677170, 2022). "The immunoreactivity for pan-keratin, vimentin, CD34 and PCNA was positive, but INI-1 was negative in the ODX1 and ODX2 tumors similar to the original EPS tumor tissue." (PMID 35677170, 2022). "Other markers including Ki67, PCNA, DAXX, CD24, CD44, CD31, MENA, Laminin, ECAD, PCAD and CDX2 and CK14 showed different trends in expression between tumour and non-tumour with qRT-PCR compared to IHC." (PMID 33906633, 2021). "As compared to the tumor, normal cells with low proliferation showed formation of γH2AX but no IGF1R/PCNA colocalization." (PMID 32701997, 2020). "Three of those genes, PCNA, ATP5C1, and NUSAP1, were confirmed to be co-expressed with TOX in tumour samples, but not in normal skin and atopic dermatitis, and as a result, they have a potential to be a diagnostic marker in CTCL." (PMID 32751918, 2020). "Adding 4μ8C significantly decreased mRNA-expression of PCNA in Huh7-cells grown in a transwell co-culture with LX2-cells, while not affecting PCNA-expression in tumor cell monocultures." (PMID 33103995, 2020). "Treatment with 4μ8C significantly decreased PCNA-mRNA-expression in the LX2+HepG2 liver scaffolds, whilst not affecting those engrafted with only tumor cells." (PMID 33103995, 2020). "Both the frequency of Sca-1 positivity, which characterizes the stem phenotype, and of PCNA positivity, which marks proliferation, were substantially (p < 0.01) reduced in IL-30-silenced tumors when compared with controls, regardless of whether the tumor hosts were WT or IL-30KO." (PMID 31366386, 2019). "Proliferating cell nuclear antigen (PCNA) is an evolutionally very well conserved multifunctional protein and a non-oncogenic protein essential for tumor cell growth and survival." (PMID 31600334, 2019). "Moreover, after treatment with the miR-199a-5p AMO, the levels of miR-199a-5p, KI-67 and PCNA significantly declined, while the protein levels of p27 and PIAS3 significantly increased, suggesting that an inhibitor targeting miR-199a-5p could remarkably suppress tumour growth in OS." (PMID 28120918, 2017). "Although final tumor volume was not distinctly different between the vec-alone and ACTA2 shRNA-overexpressing mice, expression of PCNA was decreased in ACTA2-knockdown mouse tumors." (PMID 28881584, 2017). "Consistent to the PCNA data, the proliferation rate in the GPRC5A-expressed human tumour cells did not significantly change although the EGFR level was markedly reduced." (PMID 27273304, 2016). "The xenografted tumor samples from HMG injected mice showed strong staining with TUNEL, but were negative for the growth marker of Ki67 or PCNA." (PMID 27741517, 2016). "On the contrary, TSC-inoculated mice presented numerous resting tumor cells (GFP-positive and PCNA-negative)." (PMID 26318423, 2015). "On the contrary, PCNA, cIAP-1, and XIAP were decreased in tumor tissue lysates from IL-32α Tg mice compared to non-Tg mice." (PMID 25909160, 2015).
tumor (continued). "In contrast, nearly all tumor cells and microvessel endothelial cells in the infiltrating zone were absent of PDCD10 immuno-signal (green) but showed strong PCNA immunoreactivity (red) and appeared negative for caspase 3 staining." (PMID 26490252, 2015). "Dietary treatment of mice with PEITC did not lead to changes in apoptosis index in the tumor as determined by TUNEL assay, nor did it affect the intensity of cellular proliferation marker PCNA." (PMID 22266918, 2012). "P-LISA and ELISA experiments realized from non-tumor and tumor breast cell lines revealed that that tumor cells (MDA-MD-231 and Cal-51) harbored less Dnmt1/PCNA interactions and less 5-methycytosine (5 mC) than non-tumor cells (MCF10A)." (PMID 21470401, 2011). "As SBC-2-control did not form tumours, no comparison in number of PCNA and TUNEL-positive cells was done with SBC-2-CXCR1 or SBC-2-CXCR2 tumours." (PMID 19401689, 2009). "By using immunohistochemical staining, we found that no expression of PCNA, CD44v6, and MMP-9 of the treated tumour cells was identified in the HIFU group, unlike those in the control group." (PMID 14676799, 2003). "Immunohistochemical staining showed that no expression of PCNA, MMP-9, and CD44v6 was detected within the treated tumour cells in the HIFU group, indicating that the treated tumour cells lost the abilities of proliferation, invasion, and metastasis." (PMID 14676799, 2003). "The expression levels of growth factor receptor genes (EGFR and ERBB2) and proliferation marker genes (PCNA and MKI67) in epithelial cells were not significantly higher in unaffected lung samples adjacent to a focal tumor compared with samples originating from healthy lungs." (PMID 40114924, 2025). "mRNA levels of PCNA, DAXX, laminin and CD14 in tumour tissue were equal to the levels seen in the non-tumour tissue whereas protein expression was increased for PCNA and decreased for laminin and CD14 in the tumour tissue relative to the non-tumour tissue." (PMID 33906633, 2021). "The results showed that the tumor weight in the HMGCS2 overexpression group was slightly lower than that in the control group, while the amounts of PCNA and Ki-67 nuclear signal were not significantly changed between the HMGCS2 overexpression and the eGFP control tumors." (PMID 32635582, 2020). "In tumour cell nests, the expression of SKALP/elafin was localized in the cells overlying PCNA-expressing cells and no expression was found in the cells that expressed PCNA; DNA fragmentation was often observed in the same cell layers as those in which SKALP/elafin immunoreactivity was found." (PMID 9376270, 1997). "Immunohistochemistry and western blotting analyses showed reduced protein expression of CHI3L1, PCNA, cyclin D1, Cdk 6, and MMP‐9, but the expression of cleaved caspase‐3 was increased; however, IL‐13Rα1 and IL‐13Rα2 levels were not changed in K284‐treated lung metastasis tumor tissues." (PMID 34758182, 2022). "They analyzed GSC derived from primary tumor samples by mass cytometry, and the GSC expressed normal levels of NK cell activation receptor ligands (ULBP2, ULBP3, VIM) and upregulated levels of NK cell inhibitory receptor ligands (HLA-A, HLA-B, HLA-C, HLA-E, HLA-G, PCNA) compared with non-GSC." (PMID 34638384, 2021). "In addition, vinblastine-treated tumors exhibited large stromal areas in association with a reduction in proliferation markers, including PCNA and phospho-histone H3, accumulation of collagen fibrosis, and higher levels of TUNEL staining compared with non-treated tumor tissues." (PMID 30327455, 2018).